SAMD14 (sterile alpha motif domain containing 14)
Synonyms: FLJ36890
Tractability: PROTAC: ubiquitination databases record sites on it; its protein half-life has been measured.
Gene: Protein-coding gene on chromosome 17 (50,110,040 to 50,130,160, reverse strand). Ensembl gene ENSG00000167100.
Subcellular location (Human Protein Atlas): Nucleoli fibrillar center; Nucleoplasm
Gene Ontology:
Molecular function: actin filament binding
Biological process: actin filament organization; calcium-mediated signaling; neuron projection development
Cellular component: actin cytoskeleton; cytoplasm; dendrite; postsynaptic density
Genetic constraint (gnomAD): Loss-of-function variants: 27 observed, 43.26 expected, observed/expected ratio (o/e) 0.62, 90% interval 0.46 to 0.86. The upper end of that interval is the gene's LOEUF score, 0.86, which puts it in group 3 of 6, group 1 being the genes least tolerant of losing a copy. Missense variants: 559 observed, 531.12 expected, observed/expected ratio (o/e) 1.05, 90% interval 0.98 to 1.13. Synonymous variants: 241 observed, 230.56 expected, observed/expected ratio (o/e) 1.05, 90% interval 0.94 to 1.16.
Homologues: Orthologues: chimpanzee SAMD14 (99% identical), macaque SAMD14 (98% identical), dog SAMD14 (96% identical), rabbit SAMD14 (95% identical), mouse Samd14 (94% identical), guinea pig SAMD14 (93% identical), pig SAMD14 (92% identical), rat Samd14 (81% identical), Drosophila melanogaster Spn (24% identical), Caenorhabditis elegans nab-1 (18% identical). Paralogues in human: PPP1R9A (29% identical), PPP1R9B (15% identical).
Diseases named in the same sentence as SAMD14 in open-access papers:
SAMD14 is named in the same sentence as 18 diseases in open-access papers, as found by Europe PMC text mining. Sharing a sentence is not in itself a finding about the gene and the disease. The quoted sentences say what the papers report.
central nervous system lymphoma (5 papers, 2020 to 2025). "Additionally, the facial convexity was found to be linked to the SAMD14 gene, which has previously been identified as being connected with central nervous system lymphoma and hematologic malignancy." (PMID 39928610, 2025). "Recently, neurabin-I and SAMD14 have been described as the autoantigenic target of approximately 66% of B-cell receptors (BCRs) of primary central nervous system lymphomas (PCNSL)." (PMID 33282736, 2020). "For primary central nervous system lymphoma (PCNSL), which is a specific extra‐nodal subtype of DLBCL with molecular similarities to MCD type or C5 with frequent mutations in MYD88 and CD79B, SAMD14/neurabin‐I were recently identified by us as an antigen of the BCRs." (PMID 36051037, 2022). "Knockdown of Samd14 in mice further revealed a role for Samd14 in hematopoietic stem progenitor cell function, including regulation of both myeloid and erythroid progenitor activity and secreted SAMD14 may also function as a B cell autoantigen in primary central nervous system lymphoma." (PMID 33799802, 2021).
anemia (2 papers, 2020 to 2022). A reduction in the number of red blood cells, the amount of hemoglobin, and/or the volume of packed red blood cells. "Loss of the Samd14-enhancer (Samd14–Enh) prevented anemia-induced Samd14 expression in spleen and attenuated c-Kit signaling in erythroid progenitors." (PMID 32241909, 2020). "Upregulation of Samd14 expression in anemia requires an intronic cis-regulatory element (Samd14-Enh) occupied by the transcription factors GATA2 and TAL1." (PMID 35713400, 2022). "Previous research had shown that the protein Samd14 is produced at higher quantities in individuals with anemia, and is involved with the recovery of lost red blood cells." (PMID 35713400, 2022). "As a facilitator of cell signaling that is upregulated in response to anemia, Samd14 represents a new constituent driving anemia-specific Kit activities." (PMID 35713400, 2022). "To determine if the Samd14-CP complex was dynamically regulated in anemia, we compared co-IP in control spleen to spleen isolated from PHZ-treated mice." (PMID 35713400, 2022). "To test whether CP function extends to adult stress erythropoiesis, akin to Samd14, we knocked down Capzb in the context of acute anemia induced by PHZ." (PMID 35713400, 2022). "As a first step to establishing whether Samd14 and CP complex form a cooperative functional unit to regulate erythropoiesis in anemia, we identified candidate Samd14 sequences which may mediate capping protein binding (CPB)." (PMID 35713400, 2022). "Importantly, while we used PHZ injection to induce acute anemia, Samd14 expression is also elevated in clinically relevant anemia models induced by severe bleeding and erythroid radioprotection, suggesting that Samd14 mechanisms are not specific to this model." (PMID 35713400, 2022). "Thus, Samd14–Enh-mediated up-regulation of Samd14 expression promotes c-Kit signaling in splenic progenitors to support erythrocyte regeneration during anemia." (PMID 32241909, 2020). "To rigorously establish whether Samd14–Enh deletion reduces anemia-dependent c-Kit signaling by lowering SAMD14 levels, we developed a genetic rescue assay in murine Samd14–Enh−/− primary erythroid precursor cells." (PMID 32241909, 2020). "By contrast, Samd14–Enh promotes erythrocyte regeneration and survival of mice in severe anemia." (PMID 32241909, 2020). "This enhancer confers Samd14 expression and is required for survival of mice in severe anemia." (PMID 32241909, 2020). "Anemia induces Samd14 expression, and Samd14–Enh mediates the transcriptional activation." (PMID 32241909, 2020). "In contrast to Samd14, which increases upon PHZ-induced anemia, Capzb and Capza2 mRNA and protein decreased after PHZ treatment in a population containing erythroid precursors (defined by surface markers CD71+Kit+Ter119-)." (PMID 35713400, 2022). "In response to anemia, one mechanism of stress resolution involves the GATA2-regulated activation of the Samd14–Enh intronic enhancer." (PMID 32241909, 2020). "Samd14–Enh is one of a cohort of GATA2 and anemia-activated enhancers predicted to regulate stress-dependent transcription in erythroid progenitors." (PMID 32241909, 2020). "Gata2 and Samd14 transcription are both controlled by enhancers harboring a nearly-identical conserved E-box spacer–GATA composite element, and the study of these and related enhancers established a GATA2 and anemia-activated genetic network with many potentially-critical network constituents." (PMID 32241909, 2020).
lymphoma (2 papers, 2020 to 2024). A malignant (clonal) proliferation of B- lymphocytes or T- lymphocytes which involves the lymph nodes, bone marrow and/or extranodal sites. "Fabs were then tested for specific binding against the common lymphoma BCR antigens SAMD14/neurabin-I, LRPAP1, RpoC and galectin-3 using ELISA9,10,12,21,41." (PMID 38671086, 2024). "Specific binding of the prokaryotically produced SAMD14/neurabin-I Fab-antibody to lymphoma cells and their internalization were determined by flow cytometry." (PMID 33282736, 2020). "This post-translational modification of neurabin-I and SAMD14 seems to lead to a chronic immune reaction with B-cell receptor activation contributing to lymphoma genesis of PCNSLs." (PMID 33282736, 2020).
prostate tumor (2 papers, 2021 to 2022). "Transcriptomic profiling of MCs isolated from prostate tumor region showed downregulated SAMD14 while proteomic profiling of HMC-1 demonstrated an overexpression of SAMD14." (PMID 35736421, 2022). "Transcriptomic profiling revealed a distinct gene expression profile of MCs isolated from prostate tumor regions, including the downregulation of SAMD14, a putative tumor suppressor gene." (PMID 33799802, 2021). "Overall, our data present the first profile of human MCs derived from prostate cancer patient specimens and identifies MC-derived SAMD14 as an important mediator of MC phenotype and function within the prostate tumor microenvironment." (PMID 33799802, 2021). "Combined, the data support a reduction in SAMD14 expression at both the transcript and protein level in mast cells within the prostate tumor microenvironment." (PMID 33799802, 2021). "Further investigation into the regulation of CAF matrix by SAMD14+ MC secreted proteins will provide important insight into the prostate tumor microenvironment and disease progression." (PMID 33799802, 2021). "Notably, a 12-fold enrichment of proteins associated with ECM disassembly was reported following SAMD14 overexpression in HMC-1, indicating potential regulation of the prostate tumor microenvironment through interaction with CAFs and extracellular matrix." (PMID 33799802, 2021). "It is possible that SAMD14 may regulate intracellular and extracellular functions within the prostate tumor microenvironment." (PMID 33799802, 2021). "Our data present the first profile of human mast cells from prostate cancer specimens and identify novel mast cell-derived SAMD14 as an important mediator of intercellular communication to direct matrix organization and epithelial interaction within the prostate tumor–stromal microenvironment." (PMID 33799802, 2021). "One of the top genes identified to be consistently down-regulated in MCs isolated from prostate tumor tissue compared to non-tumor tissue across multiple patients was SAMD14 (Sterile α-Motif Domain containing protein 14)." (PMID 33799802, 2021). "Semi-quantitative analysis of SAMD14+ staining intensity in tryptase+ mast cells across 3 individual patients (Validation cohort) revealed a significant reduction in the percentage of SAMD14+ mast cells within prostate tumor sections compared to non-tumor prostate tissue." (PMID 33799802, 2021).
B‐cell lymphoma (1 paper, 2023). "Still, the BAR‐body concept may be a powerful tool as an additional future treatment option for B‐cell lymphomas considering that several B‐cell lymphoma autoantigens have already been identified, including LRPAP1, neurabin‐I/SAMD14, and Ars2." (PMID 36819155, 2023).
osteoarthritis (1 paper, 2019). A noninflammatory degenerative joint disease occurring chiefly in older persons, characterized by degeneration of the articular cartilage, hypertrophy of bone at the margins and changes in the synovial membrane. "Thus, lnc-SAMD14-4 may play a key role in the pathogenesis of osteoarthritis by promoting the expression of the COL1A1 and COL1A2 genes." (PMID 31534838, 2019).
prostate carcinoma (1 paper, 2021). A carcinoma that arises from epithelial cells of the prostate gland. "Here, we identify a gene called SAMD14 that is reduced in mast cells obtained from men with prostate cancer." (PMID 33799802, 2021).
Sepsis (1 paper, 2023). Sepsis is defined as life-threatening organ dysfunction caused by a dysregulated host response to infection. "sepsis was associated with the C11_Plate cluster, and ESAM, HBG2, MMRN1, PF4V1, SAMD14, SELP, and TGFB1I1 may be important in this context." (PMID 37919720, 2023).
tumor (2 papers, 2021). "To validate the reduction of SAMD14 in MCs isolated from tumor regions (MC-T), we assessed SAMD14 transcript expression in an independent cohort of patient-matched prostate MCs (n = 4; Validation cohort)." (PMID 33799802, 2021). "Together, these results support the role of SAMD14+ mast cells in promoting a ‘normalized’ extracellular matrix reflective of the non-tumor prostate microenvironment." (PMID 33799802, 2021). "Our data reveal a novel role for MC-derived SAMD14 in regulating their microenvironment via the remodeling of CAF-derived matrix and promotion of pro-tumor prostate epithelium." (PMID 33799802, 2021).
cancer (1 paper, 2021). A tumor composed of atypical neoplastic, often pleomorphic cells that invade other tissues. "We demonstrate that SAMD14 expression in mast cells can alter their secretions and promote the alignment of matrix fibers that cancer cells use to attach and move around on." (PMID 33799802, 2021).
infection (1 paper, 2022). The state of being infected such as from the introduction of a foreign agent such as serum, vaccine, antigenic substance or organism. "GFPlow cells were FACS purified at 48 hr post-infection and Samd14-∆38–54, Samd14-∆114–124, Samd14-∆170–180, and Samd14-∆272–295 proteins were IPed using anti-HA agarose beads." (PMID 35713400, 2022). "Capzb knockdown in PHZ-treated erythroid precursors decreased Capzb expression twofold (p=0.016) and decreased Capzβ protein compared to control infections with no change in Samd14 expression." (PMID 35713400, 2022).
SAMD14 also shares sentences with these, for which no sentence is quoted: Autoimmunity (1 paper); chronic lymphocytic leukemia (1); diffuse large B-cell lymphoma (1); hematologic malignancy (1); mantle cell lymphoma (1); metastatic tumor (1); plasma cell dyscrasia (1).